NPY (neuropeptide Y)
Diseases named in the same sentence as NPY in open-access papers (continued):
Sharing a sentence is not in itself a finding about the gene and the disease.
depression (continued). "Third, neuropeptide Y might be a possible marker in the relationship between depression and low BP level." (PMID 32099584, 2020). "Meanwhile, depression is characterised by altered levels of neuropeptide Y." (PMID 32665058, 2020). "It has been suggested that impaired metabolism of plasma neuropeptide Y in depressed patients could be involved in the pathogenesis of depression." (PMID 32665058, 2020). "It has been reported that NPY is involved in the pathologic process of depression." (PMID 31736656, 2019). "Studies that have identified a link between low BP and depression also suggested that cerebral vascular perfusion is a contributing factor, and that overexpression of neuropeptide Y observed in both depression and low BP may mediate this relationship." (PMID 29490622, 2018). "In addition, pre-clinical and clinical studies indicate NPY involvement with depressive-like behavior and depression, respectively." (PMID 30131681, 2018). "On the other hand, low NPY levels are found in the cerebrospinal fluid of depressed patients and in genetic-, lesion-, and stress-induced animal models of depression." (PMID 30131681, 2018). "Furthermore, the behavioral indicators of depression showed strong correlations with the serum levels and the hippocampal content of NPY." (PMID 28582442, 2017). "The finding of higher NPY and CGRP CSF levels in PD patients with MDD raises the possibility that different pathophysiological processes may underlie depression in PD and MDD." (PMID 28659833, 2017). "It was postulated that neuropeptides, especially NPY, might play a significant role in the pathophysiology of depression." (PMID 27975125, 2017). "The effects of NPY on depression are still not clearly known." (PMID 29062372, 2017). "Nevertheless, Domschkeet al. compared this polymorphism with other alleles of NPY and found that this particular rs16139 is not related to the perceived effects of treatment and prognosis of patients with depression." (PMID 29062372, 2017). "The increase in the level of Y5R protein in that astrocyte ablation model may be a compensatory reaction to the postulated decrease in NPY function in depression." (PMID 27975125, 2017). "A reduction of the central NPY level and/or function was observed in experimental and clinical depression, whereas central administration of NPY or Y1R agonist [Leu31,Pro34]-PYY produced antidepressant-like effects in rats and mice; moreover, these effects were blocked by Y1R antagonists." (PMID 27975125, 2017). "Taken together, the evidence suggested that low NPY increased the risk for depression through adding sensitivity to negative stimuli and declining brain reserve capacity at the cellular levels and also possibly at the neural circuit levels." (PMID 28082897, 2016). "Moreover, the selected analyte of NPY mRNA expression, potentially provide new insights into exploring the molecular mechanism of different subtypes of depression." (PMID 28082897, 2016). "It was consistent with the results of ROC and logistic regression analyses, which showed that NPY mRNA could be conducive to distinguish different subtypes of depression (PSD and MDD; AUC = 0.766)." (PMID 28082897, 2016). "Because evidence of elevated LC activity has been linked to depression and PTSD this NPY-induced brake on LC over activation may therefore promote stress resilience." (PMID 25206349, 2014). "Therefore, investigating the efficacy of intranasal NPY for PTSD and depression as well as mitigating CVD risk in these patients will be critical." (PMID 25206349, 2014). "Moreover, in a rat model of depression, voluntary running had antidepressant-like effects in behavioral tests and in parallel enhanced NPY expression and neurogenesis." (PMID 23422934, 2013). "In addition, NPY is involved in the characteristic functions of the nucleus accumbens via Y1, such as in alcohol consumption, drug dependence, food intake, anxiety, and depression." (PMID 39585059, 2024).
depression (continued). "It is speculated that the lack of a relationship between being overweight and depression may be due to leptin absence or neuropeptide Y, which are associated with depressive symptoms." (PMID 36354390, 2022). "NPY and T might be the effective targets for treating depression and infertility." (PMID 35432561, 2022). "Moreover, reports also demonstrated the function of neuropeptides in nervous system could be modulated by EPACs pathway, such as NPY is reported to regulate fear behaviours, human depression, and other neuropsychiatric disorders via EPAC pathways." (PMID 35011543, 2022). "Depression has been shown to present with impaired salience network mediated switching into the central executive network, which may relate to the lower switching likelihood within the salience network shown here by the low-NPY group." (PMID 34867217, 2021). "Additionally, NPY levels in the CSF were lower in patients with reactive and first-episode depression, and its plasma levels were lower in patients with recurrent major depression as compared to controls." (PMID 32867327, 2020). "However, NPY expression in the brain decreases overall during depression." (PMID 33123166, 2020). "In another study, intracerebroventricular administration of NPY in olfactory bulbectomized rats, a rodent model of depressive-like symptoms, resulted in attenuation of increased behavioral irritability, indicating a possible therapeutic role of NPY in reducing depression-like behaviors." (PMID 28824541, 2017). "Taken together, the increase in the level of Y5R protein in our astrocyte ablation model suggests that Y5R may play an important role in this model of depression and that the blockade of Y5R has been hypothesized as an indirect way to increase NPY function and improve depression-like behavior." (PMID 27975125, 2017). "In addition, Neuropeptide Y (NPY) may explain the association between increase in body weight and reduction in severity of depression." (PMID 28378748, 2017). "Moreover, the NPY mRNA expression can identify the different types of depression to some extent." (PMID 28082897, 2016). "Hence, disruptions in the NPY system could potentially be involved in both schizophrenia and depression, while also linking both disorders to metabolic conditions, appetite changes, and obesity." (PMID 25762938, 2015). "The levels of neuropeptide Y (NPY), testosterone (T), and IL-1β, IL-6, TNF-α, IL-10, and IL-4 in the peripheral blood plasma of normal people, patients with depression, and patients with DCMI were measured." (PMID 35432561, 2022). "Additionally, since neuropeptide Y, which comprises 36 amino acids, is involved in the relationship between weight gain and the attenuation of depressive symptoms, a decrease in its neurotransmitters may be related to depression." (PMID 36354390, 2022). "BDNF, NPY, and TNF have been reported to be involved in the regulation of depression mediated by ELS, showing sex differences, too." (PMID 35663561, 2022). "Several studies report on altered NPY levels in plasma and/or CSF in posttraumatic stress disorder (PTSD), major depressive disorder (MDD), and chronic stress." (PMID 34267682, 2021). "The NPY system is emerging as an important therapeutic target for preventing or reducing the incidence of neuropsychiatric disorders such as PTSD and depression." (PMID 32867327, 2020). "Neuropeptides, such as neuropeptide Y (NPY), substance P, and galanin (GAL), were found to be affected by stress or to be involved in stress response, in some animal models or human depression patients." (PMID 33100903, 2020). "NPY played an antidepressant role in the mPFC by suppressing the NLRP3 signaling pathway, mainly via Y2R, in the LPS-induced depression model rats." (PMID 31736656, 2019).
depression (continued). "In addition, leptin was shown to be responsible for the inhibition of the Neuropeptide Y (NPY) neurons, which is known to have a specific anxiolytic and neuroprotective properties, and is proposed to play a critical role in mediating chronic stress in patients with depression." (PMID 31354416, 2019). "The LIMMA analysis first detected a number of down-regulated genes in individuals with EDs that are known to be suppressed in schizophrenia or major depressive disorder, such as SST, NPY, SLC32A1, HINT1, and RELN." (PMID 29958387, 2018). "In another genetic animal model of depression, the Flinders Sensitive Line (FSL) rats, decreased NPY protein was found in the hippocampal CA region, while Y1 binding sites were increased." (PMID 28824541, 2017). "Our results showed strong inverse correlation between depression state (expressed by means of immobility time in TST) and NPY content in CA1, CA2/3 and DG." (PMID 28582442, 2017). "Considerable evidence indicates that in the CNS neuropeptide Y (NPY) can attenuate the response to stress, and has therapeutic potential for PTSD as well as for depression." (PMID 28469551, 2017). "Neuropeptide Y (NPY) is the most abundant neuropeptide widespread in different brain regions with an important role in the regulation of basic physiological functions, and may be connected to several psychiatric disorders, including depression and related illnesses." (PMID 28582442, 2017). "The levels of NPY and CGRP were higher in PD patients with depression compared to major depressive disorder patients." (PMID 29158943, 2017). "These are the first data regarding the regulation of NPY and CGRP in PD and comparing these two peptides in PD with comorbid depression to MDD." (PMID 28659833, 2017). "In PD patients, the correlations between NPY and 5-HIAA and CGRP and 5-HIAA were r = 0.50 and r = 0.06; in PD patients with comorbid depression, they were r = 0.25 and r = 0.26 and in MDD patients, they were r = −0.14 and r = −0.47." (PMID 28659833, 2017). "Our results show that both NPY and CGRP in CSF are higher in PD patients with comorbid depression compared to MDD patients." (PMID 28659833, 2017). "The strength of the study is that, to the best of our knowledge, this is the first time that differences in NPY and CGRP CSF levels between PD patients with comorbid depression and MDD patients have been reported." (PMID 28659833, 2017). "In conclusion, the present study demonstrates that NPY is abnormal in stroke, PSD and MDD patients and it has a significant distinguished function in the different subtypes of depression." (PMID 28082897, 2016). "Pharmacological interventions targeting the neurochemical systems involving NPY, BDNF, CRH, and HPA axis, among others, are being investigated as potential treatments for depression and PTSD." (PMID 23422934, 2013). "Instead, age emerged as a robust determinant of circulating NPY levels, independent of depression status and BMI, after adjustment for sex." (PMID 42098897, 2026). "In addition to these classical neurotransmitter systems, the role of vasopressin and neuropeptide Y (NPY) neuropeptides in the context of HPA axis activation and depression is gaining attention." (PMID 40305200, 2025). "Since NPY cannot yet be routinely administered to patients, we investigated the effects of sitagliptin, a dipeptidyl peptidase-4 (DPP4) inhibitor approved for the treatment of type 2 diabetes mellitus, on social fear and comorbid depression in mice." (PMID 40490517, 2025). "SGB effectively improves GAD symptoms and sleep quality in patients without comorbid depression, potentially via modulation of NE, 5-HT, and NPY pathways." (PMID 40401023, 2025). "To investigate the differences in the expression of inflammatory factors in the serum of normal person, patients with depression, and patients with DCMI, we performed ELISA to detect the levels of NPY, T, IL-1β, IL-6, TNF-α, IL-10, and IL-4 in the peripheral blood plasma." (PMID 35432561, 2022).
depression (continued). "A recent study of depression in mice shows that the impact of HFD lengthened behavior, as a consequence of a decrease in the expression of NPY in the hypothalamus and pituitary, while the levels of NPY and the DPP-IV activity increased in plasma." (PMID 34836194, 2021). "The severity of depression symptoms measured with the BDI scale did not predict the NPY concentration in all of the included participants, although the results were at the borderline of statistical significance (p = 0.059)." (PMID 33670342, 2021). "In addition, it increases the level of the neuroprotective molecules brain-derived nerve growth factor (BDNF) and neuropeptide Y (NPY), which are also found to be decreased in patients with depression." (PMID 34204057, 2021). "All these results suggest that NPY and Y2R in the mPFC are involved in the pathophysiology of depression and NPY plays an antidepressant role in the mPFC mainly via Y2R, which suppresses the NLRP3 signaling pathway, in LPS-induced depression model rats." (PMID 31736656, 2019). "However, MAI stimulation at SP6 significantly reduced estrogen deficit-induced depression-like behaviors and increased BDNF and NPY." (PMID 29643431, 2018). "The levels of NPY in PD patients, without or with comorbid depression, and in patients with MDD were 64.4 ± 21.9, 83.1 ± 25.2, and 46.8 ± 17.0 pmol/L, respectively." (PMID 28659833, 2017). "Both NPY and CGRP were higher in PD patients with comorbid depression compared to MDD patients." (PMID 28659833, 2017). "Studies on the NPY levels in patients with major depression are not completely consistent, which can reflect the complexity of the etiology of depression." (PMID 23468908, 2013). "In 42 patients with CFS, plasma NPY had significant correlations (<0.05) with perceived stress, depression, anger/hostility, confusion, negative thoughts, positive thoughts, general health, and cognitive status." (PMID 21190576, 2010). "The effect of medications such as cholesterol lowering, pain or anti-depression on plasma NPY is not known." (PMID 21190576, 2010). "The significant correlations of NPY with stress, negative mood, general health, depression and cognitive function strongly suggest that this peptide be considered as a biomarker to distinguish subsets of CFS." (PMID 21190576, 2010). "Similarly, a study using the FSL rat model of depression revealed that the antidepressant treatments employed in the PST, including running and the combination therapy with escitalopram and a running wheel, significantly increased the NPY mRNA." (PMID 36829752, 2023). "Neuropeptide Y (NPY) is discussed to be a key mediator of resilient vs. vulnerable adaptations and specifically, the NPY-Y2 receptor (Y2R) may be involved in the pathophysiology of depression due to its negative regulation of NPY-release." (PMID 35846564, 2022). "However, a different study in male Sprague–Dawley rats found that NPY infusion into the infralimbic cortex subregion of the mPFC did not affect depression-like behavior in the forced swim test." (PMID 33192369, 2020). "Additionally, infusion of NPY into the IL impairs retrieval of fear extinction without affecting depression-like behavior or working memory." (PMID 28824541, 2017). "This study was aimed to examine protein and mRNA expression levels of NPY in 159 cases with four groups including post-stroke depression (PSD) group, stroke without depression (Non-PSD) group, major depressive disorder (MDD) group and normal control (NC) group." (PMID 28082897, 2016). "As NPY and VGF also actively participate in the neurotrophic hypothesis of depression and could be regulated by BDNF, our data argue that both BDNF and its downstream neurotrophic peptides, NPY and VGF, may play a role in the antidepressant effects of exercise." (PMID 25477997, 2014).
depression (continued). "Our finding that NPY positively correlated with perceived stress, anger, depression, negative thoughts and maladaptive coping in patients with CFS suggests that NPY will be useful in defining subsets of patients for clinical trials and as a measure of therapeutic effects." (PMID 21190576, 2010). "Neuropeptide Y (NPY) is involved in the body’s stress response and is found in higher concentrations in the sweat of patients with depression than in that of people without depression." (PMID 36597511, 2023). "Meanwhile, EA could increase hippocampus 5-HT to improve depression in CUMS model and adrenal NPY with no significance noted in circulating NE in cold stress model and serum inflammation in murine asthma model." (PMID 29021740, 2017). "Therefore, the first aim of this study was to explore the changes of NPY protein content and mRNA expression in PSD, stroke without depression (Non-PSD) and MDD patients." (PMID 28082897, 2016). "Svenningsson and coworkers examined the levels of NPY, CGRP, and 5-hydroxyindoleacetic acid (5-HIAA), the major serotonin metabolite, in cerebrospinal fluid (CSF) from PD patients, with or without comorbid depression, and compared them to the levels in patients with major depressive disorder." (PMID 29158943, 2017).